GZMB (granzyme B)
Diseases named in the same sentence as GZMB in open-access papers (continued):
Sharing a sentence is not in itself a finding about the gene and the disease.
Sepsis (continued). "The most modulated genes were Granzyme B, Complement Factor B, Complement Component 4 Binding Protein Alpha, IL-12, and SERPINB-1 that were closely related to sepsis-induced immunological process." (PMID 33868226, 2021). "Although GzmB deficiency does not increase survival during endotoxemia or bacterial sepsis, some of the biological functions of this protease might contribute to some of the vascular alterations observed in sepsis." (PMID 32655547, 2020). "HIV positive sepsis patients in both ICU cohorts showed overexpression of genes involved in granzyme signaling (GZMA, GZMB), cytotoxic T-cell signaling (CD8A, CD8B) and T-cell inhibitory signaling (LAG3), compared to HIV negative patients." (PMID 26871709, 2016). "However, downregulated genes in sepsis NK cells similarly included cytotoxicity-related genes (GZMH, GNLY & GZMB, -1.42log2FC, -1.29log2FC & -0.48log2FC, respectively)." (PMID 41208955, 2025). "In conclusion, the genes GNLY, GZMB, PRF1, and RASGRP1 exhibited significant upregulation in the normal control group and downregulation in the sepsis group, thereby displaying a positive correlation with the prognosis of sepsis patients." (PMID 38057716, 2023). "GNLY, GZMB, PRF1, and RASGRP1 are lysosome-related genes that are closely related to the prognosis of sepsis, and may be used as new research targets for sepsis and provide direction for lysosome-targeted therapy." (PMID 38057716, 2023). "Notably, the analysis revealed that GNLY, GZMB, PRF1, and RASGRP1 exhibited significantly higher expression levels in the normal control group compared to the sepsis group (P<0.05)." (PMID 38057716, 2023). "Finally, as it will be discussed in the next section, it has been found that GzmB is expressed in platelets during sepsis using a mouse polymicrobial peritoneal sepsis model and might contribute to some of the alterations in vascular biology observed during sepsis." (PMID 32655547, 2020). "GZMA and GZMB were under-expressed in sepsis patients without HIV infection, but not in HIV positive sepsis patients, and differences in granzyme signaling were not apparent in asymptomatic HIV patients." (PMID 26871709, 2016). "In our preclinical experiments, the absence of granzyme B or treatment with eptifibatide resulted in less severe sepsis and extended survival." (PMID 22844498, 2012). "This builds on prior work demonstrating that granzyme B is upregulated in septic shock non-survivors and further solidifies the important role played by this enzyme in platelets during sepsis." (PMID 22844498, 2012). "In sepsis, platelet granzyme B-mediated apoptosis occurs in spleen and lung, and absence of granzyme B slows sepsis progression." (PMID 22844498, 2012). "In contrast, there was a lack of TUNEL staining in spleens and lungs from septic granzyme B null mice and these mice survived longer following induction of sepsis than wild type mice." (PMID 22844498, 2012). "Additionally, healthy controls were not included to compare their plasma granzyme B levels with those of patients with sepsis." (PMID 40094854, 2025). "In addition, these results are strengthened by a significantly lower cytotoxic module score (calculated using the AddModuleScore function in Seurat V4 using the cytotoxic-related genes GZMH, GZMK, GZMA, GZMB, PRF1, and GNLY) in all sepsis cytotoxic cell subsets compared to bacteraemia and controls." (PMID 41208955, 2025). "Baseline GzmB expression of NK-cells was not impacted by sepsis." (PMID 30379932, 2018). "However, the results obtained were not consistent and a clear conclusion on the role of GzmA and/or GzmB in bacterial control and sepsis could not be reached." (PMID 34815792, 2021). "Last but not least, it has been reported that GzmB may act on some of components of the EC involved in fibrillogenesis such as fibrillin-1 or decorin, increasing vascular permeability, one of the most important pathological events that occur in sepsis." (PMID 32655547, 2020).
Sepsis (continued). "First, biomarkers of T-cell activation and IFNγ-activity (e.g. GZMB, PDL1, LAG3, CXCL9) were present broadly in IHF, including hyperferritinemic sepsis, and were not unique to one diagnosis (PC1)." (PMID 39264477, 2024). "Principal component analysis of GZMA, GZMB, CD8A, CD8B, KLRD1, PRF1 and LAG3 gene expression revealed 81% explained variance for the first principal component considering HIV negative and HIV positive sepsis patients." (PMID 26871709, 2016).
hepatocellular carcinoma (25 papers, 2014 to 2025). A malignant tumor that arises from hepatocytes. "A meta-analysis found that GZMB+ lymphocytes were significantly associated with a better overall survival (OS) for patients with hepatocellular carcinoma (HCC) and colorectal cancer." (PMID 34454491, 2021). "A truncated form of NPM1 found in some hepatocellular carcinoma tissue formed an unusually stable oligomer and showed increased susceptibility to cleavage by granzyme B. Initiation of translation at the seventh methionine generated a protein (M7-NPM) that shared all these properties." (PMID 25490769, 2014). "Annexin A2 also promotes immune escape of hepatocellular carcinoma, by upregulation of immune checkpoint molecules, and decreased expression of effector factors, including perforin, granzyme B (GZMB), interferon-γ, and TNF-α." (PMID 38519766, 2024). "In addition, the release of HSP90-Exs by human hepatocellular carcinoma cells has been shown to activate NK cell cytotoxicity, as well as granzyme B production, which is an important factor in the development of a positive tumor immune microenvironment." (PMID 39911383, 2025). "In vivo, hepatocellular carcinoma (HCC) intertumoral transfer of PD1-deficient DCs promote CD8 T cell infiltration as well as their cytotoxicity through the increased expression of perforin and granzyme B, enhancing antitumor immunity." (PMID 41177809, 2025). "Notably, ZOL-induced blood Vγ9Vδ2 TRM exhibited higher IFN-γ and Granzyme B expression than ex vivo isolated liver Vγ9Vδ2 TRM following co-culture with hepatoma cell lines." (PMID 35296658, 2022). "When investigated in a model of hepatocellular carcinoma and colorectal cancer, HSP60-Exs have the ability to stimulate cytotoxicity and granzyme B production in NK cells." (PMID 39911383, 2025). "In patients with hepatocellular carcinoma (HCC), neoplasm-localized MAIT cells exhibited upregulation of inhibitory immune molecules (e.g., PD-1, CTLA-4, and TIM-3) and secreted lower quantities of effector molecules (e.g., IFN-γ, granzyme B, and perforin)." (PMID 36463401, 2023). "Moreover, Th9 cells can also secrete granzyme B and directly participate in the killing of tumor cells, but only one report has proven that Th9 cells exert a tumorigenic role in human hepatocellular carcinoma (HCC)." (PMID 32228589, 2020). "In hepatocellular carcinoma (HCC), tumor tissue localized MAIT cells also exhibited exhausted phenotype with upregulation of inhibitory immune molecules (PD-1, CTLA-4, and TIM-3) and secreted lower quantities of effector molecules (e.g., IFN-g, granzyme B, and perforin)." (PMID 38545100, 2024). "TIB appear to play an important role in mediating control of hepatocellular carcinoma (HCC), in addition to TIL expressing granzyme B and IFN-γ62." (PMID 30459443, 2018).
vitiligo (25 papers, 2012 to 2025). Generalized well circumscribed patches of leukoderma that are generally distributed over symmetric body locations and is due to autoimmune destruction of melanocytes. "GzmB plays a causal role in the development of pemphigoid disease and carries diagnostic and prognostic significance in cutaneous lupus erythematosus, vitiligo, and alopecia areata." (PMID 36830757, 2023). "Genome-wide association studies (GWAS) have identified more than 50 genetic risk variants for vitiligo, including genes related to cytolysis (GZMB, CTLA4, FOXP3) and melanocyte function (TYR, MC1R, XBP1)." (PMID 36182982, 2022). "Our positive results provide additional supportive evidence that GZMB gene is an important locus for vitiligo in Han Chinese population, and are useful for informative assessment of genetic risk for vitiligo in Han Chinese individuals." (PMID 30158536, 2018). "Our results would provide clues for understanding the roles of GZMB in the genetic predisposition of vitiligo." (PMID 30158536, 2018). "GzmB may also carry diagnostic and prognostic significance in cutaneous lupus erythematosus, vitiligo, and alopecia areata/scarring alopecia." (PMID 36830757, 2023). "GZMB encodes the enzyme Granzyme B, which plays an important role in cytotoxic T cell-induced apoptosis, and it has been considered one of the candidate genes for vitiligo because of its connections with human immune system." (PMID 30158536, 2018). "In addition to conferring a genetic predisposition to vitiligo, GzmB may offer clinical relevance as a diagnostic and prognostic tool." (PMID 36830757, 2023). "For example, CD49a+ TRM cells—co-expressing CD103—are enriched in lesional vitiligo skin and display enhanced cytotoxicity, granzyme B/perforin production, and stronger IL-15 responsiveness." (PMID 40791580, 2025). "The frequency of CD49a+CD103+CD8+ TRM cells secreting Prf1 and GzmB was increased in the vitiligo lesions of patients, suggesting that the production of IL-2 or IL-15 is enriched in the environment of vitiligo areas." (PMID 39193473, 2024). "IL-15 (as well as IL-2) activates CD49a+CD8+ resident memory T lymphocytes in human vitiligo skin and induces perforin and GZMB in those cells, followed by melanocyte apoptosis." (PMID 38673994, 2024). "The second is Granzyme B. Downregulation of immunosuppressive gene GZMB in the Treg cells of vitiligo patients can lead to the decrease of the inhibitory function of Treg and aggravate the vitiligo." (PMID 37207234, 2023). "Others have similarly observed elevated expression of GzmB in vitiligo patients’ skin biopsies, plasma samples, or both." (PMID 36830757, 2023). "Other candidate loci for vitiligo in several ethnicities include FASLG, a member of the TNF superfamily, and GZMB, a protease, both of which point to a role of dysregulated apoptosis in vitiligo." (PMID 35643735, 2022). "The results show that IFN-γ, CXCL9, CXCL10, and GzmB are highly expressed in the skin blister interstitial fluid and plasma of vitiligo compared to healthy controls." (PMID 35464413, 2022). "We investigate the feasibility of IFN-γ, CXCL9, CXCL10, and GzmB as prognosis predictors for vitiligo." (PMID 35464413, 2022). "Further studies are needed to investigate the pathological role of IFN-γ and GzmB in the pathogenesis of vitiligo, aside from merely a marker for cytotoxic T cells." (PMID 35464413, 2022). "We further study the plasma expression of IFN-γ, CXCL9, CXCL10, and GzmB in active and stable vitiligo compared to healthy control." (PMID 35464413, 2022). "IFN-γ and its’ signature cytokines, including CXCL9, CXCL10, and GzmB, are most highly expressed in the vitiligo patients’ lesion skin interstitial fluid and plasma compared to healthy control." (PMID 35464413, 2022). "Our study showed that IFN-γ and its’ signature cytokines, including CXCL9 and CXCL10, and GzmB, are most highly expressed in the vitiligo patients’ blister and plasma compared to healthy control." (PMID 35464413, 2022).
vitiligo (continued). "Other discoveries indicated that IFN-γ and granzyme B are the key cytokines partaking in the course of vitiligo, because they stimulate the apoptosis of melanocytes." (PMID 32443482, 2020). "Two studies showed that IFN‐γ and granzyme B are key cytokines in the pathogenesis of vitiligo because they induce melanocyte apoptosis." (PMID 31230406, 2019). "In line with this, another study reported an enrichment of IFN‐γ‐producing CD49a+ CD103+ CD8+ TRM cells in vitiligo lesions, with a rapid granzyme B and perforin production response upon IL‐15 stimulation." (PMID 31230406, 2019). "Our immunofluorescence results have shown that indeed, cytotoxic NK cells (defined as CD56 + Granzyme B+) containing IFNγ (CD56 + IFNγ+) were present in NL human vitiligo skin." (PMID 31097717, 2019). "Our positive results provide additional supportive evidence that GZMB gene is an important locus for vitiligo in Han Chinese population." (PMID 30158536, 2018). "The effects of GzmB knockout or inhibition in vitiligo should be further examined." (PMID 36830757, 2023). "In spite of evidence nominating GzmB as a potential predictive biomarker and therapeutic target in vitiligo, causality has not been established." (PMID 36830757, 2023). "In addition, this study also uncovered the significantly elevated expression profile of GzmB in the skin and plasma is less reported in vitiligo pathogenesis." (PMID 35464413, 2022). "IFN-γ, CXCL9, CXCL10, and GzmB are highly expressed in vitiligo patients’ lesion skin and plasma and may serve as biomarkers for the clinical activity, severity, and prognosis prediction in vitiligo patients." (PMID 35464413, 2022). "In addition to cellular cytotoxicity, TRMs secrete IFN-γ, perforin and granzyme B, which are essential for inducing melanocyte apoptosis in vitiligo." (PMID 34445713, 2021). "In addition, the NK cells cultured from vitiligo skin explants exhibited high levels of the serine protease, granzyme B, indicating that these cells are highly active and capable of exerting cytotoxicity on the target cells by contact." (PMID 23251420, 2012). "In different vitiligo cells, Granzyme B may play different roles." (PMID 37207234, 2023). "In conclusion, our results show that IFN-γ, CXCL9, CXCL10, and GzmB are highly expressed in vitiligo patients’ lesion skin and plasma and may serve as biomarkers for the clinical activity, severity, and prognosis prediction in vitiligo patients." (PMID 35464413, 2022). "Furthermore, aside from pro-apoptotic function, studies have shown that GzmB is responsible for the cleavage of the extracellular matrix that contributes to the collapse of hair follicle immune privilege in alopecia areata, a close disease to vitiligo." (PMID 35464413, 2022). "CD49a+CD8+TRM are even poised for cytotoxic responses by producing perforin and granzyme B.176CD8+TRM residing around hair follicular might also curtail the entry of melanocyte precursors from the follicular reservoir to vitiligo lesions, thus conferring disease flares or repigmentation blockade." (PMID 33200838, 2021). "Some cytokines such as KLRG1+ lymphocytes secrete cytotoxic molecules (granzyme B and perforin), inflammatory cytokines (IFN-γ and TNF-α), and inflammatory chemokine receptors (CCR5 and CX3CR1) are involved in gene expression, which are associated with vitiligo." (PMID 33679890, 2021). "In vitro, T-96 decreased the proliferation, CD69 membrane expression, and IFN-γ, granzyme B, (GzmB), and perforin (PRF) levels in CD8+ T cells isolated from patients with vitiligo." (PMID 37403086, 2023). "ROC curve analysis shows that the levels of IFN-γ appear to be most sensitive and specific in diagnosing active vitiligo, followed by CXCL-10 and GzmB." (PMID 35464413, 2022). "Due to their ability to produce and secrete perforin, IFN-γ, and granzyme B, TRM cells demonstrate a cytotoxic effect on melanocytes, thus inducing depigmented lesions in the course of the vitiligo." (PMID 32443482, 2020).
vitiligo (continued). "Additionally, 3D‐Exos markedly attenuated the expression levels of the activation marker cluster of differentiation 69 (CD69), interferon‐gamma (IFN‐γ), and Granzyme B in CD8+ T cells in both the tail skin and peripheral blood of vitiligo mice." (PMID 38887870, 2024). "Compared with normal controls, CD8+LEPR+ T cells in the peripheral blood of patients with vitiligo showed enhanced expression of cytotoxic cytokines, and the expression of IFN-γ, Granzyme B, and perforin in CD8+LEPR+ T cells was higher than that in CD8+ LEPR- T cells." (PMID 37207234, 2023). "While minimal to absent in healthy skin, GzmB is markedly elevated in alopecia areata, interface dermatitis, pemphigoid disease, psoriasis, systemic sclerosis, and vitiligo." (PMID 36830757, 2023). "However, the levels of IFNG, PRF1, GZMB and CXCR3, CXCL9, CXCL10, CXCL12, and other cytokines also had an upward trend in the vitiligo group." (PMID 37207234, 2023). "Other studies have suggested that perforin and Granzyme B expressed by CD8+ T cells can directly lyse target cells, and melanocyte specific cytotoxic CD8+ T cells have been detected in blood and skin lesions of vitiligo patients." (PMID 37207234, 2023). "Intriguingly, granzyme B (GzmB), a key effector of cytotoxic T cells, is highly expressed in the lesion and non-lesion skin and plasma of vitiligo patients compared to healthy controls." (PMID 35464413, 2022). "Whereas NDGA, as a well-known 5-LOX inhibitor, could significantly inhibited the expression of IFN-γ, granzyme B and perforin of CD8+ T cells derived from vitiligo patients." (PMID 35222431, 2022). "Activated NK cells (CD56+ / granzyme B+) and IFNγ-producing cells have been identified in the blood and non-lesional skin of patients with vitiligo." (PMID 35643735, 2022). "Additionally, disease activity and severity-based analyses revealed significantly decreased GZMB (p = 0.019 and 0.034), SERPINB9 (p = 0.031 and p = 0.035), and ITPR1 (p = 0.0003 and p = 0.034) transcripts in active vitiligo and severe GV patients' Tregs." (PMID 36157881, 2022). "In this study, the protein level of GZMB was not measured in the skin or PBMCs of vitiligo patient and controls." (PMID 33431938, 2021). "Semi-quantification of their detection has shown significantly higher number of CD56 + Granzyme B+ cells and CD56 + IFNγ+cells in NL compared to L skin of vitiligo patients (n = 6) and a higher number in NL skin of vitiligo patients compared to healthy skin (n = 5)." (PMID 31097717, 2019). "Most notably, CLE and DM lesions were enriched for Th1-skewed CD4+ T cells that, unlike their counterparts in vitiligo, expressed cytotoxic effector molecules including GZMB, GZMK, and PRF1, a population nearly absent in healthy and psoriasis skin (scCODA FDR < 0.1)." (PMID 40894544, 2025). "However, our results showed that celecoxib couldn’t influence the expression of IFN-γ, as well as granzyme B and perforin generated by CD8+ T cells in vitiligo patients." (PMID 35222431, 2022). "However, unlike NK cells, ILC1s lack direct cytotoxic capacity and do not contain perforin or granzyme B. Compared to ILC1 and NK cells, ILC2 has been less studied in vitiligo." (PMID 41169396, 2025).